IL22 (interleukin 22)
Diseases named in the same sentence as IL22 in open-access papers (continued):
Sharing a sentence is not in itself a finding about the gene and the disease.
tuberculous pleurisy (3 papers, 2013 to 2024). "It is widely accepted that IL-10, IL-22 and IL-26 inhibit the pathological progression of tuberculous pleurisy by suppressing inflammatory responses while promoting local immune responses." (PMID 39003443, 2024). "In addition, CD4+ T cells expressing different combinations of IFN-γ, IL-2, TNF-α, IL-17A, and IL-22 have been described in tuberculous pleurisy." (PMID 23451159, 2013). "More importantly, sorted NK cells from the patients with tuberculous pleurisy stimulated with LPS did not produce IL-22 or IFN-γ, indicating that the response of NK cells to BCG was TB-antigen specific." (PMID 27031950, 2016).
vitamin A deficiency (3 papers, 2021 to 2023). Deficiency of vitamin A due to malnutrition, malabsorption, or dietary lack. "The results show that vitamin A deficiency decreased the ADG, villus height, villus height/crypt depth ratio and mRNA expression levels of IL-22, Occludin and ZO-1." (PMID 34071204, 2021). "In the mouse model of vitamin A deficiency, supplementation of β-carotene also downregulated the levels of intestinal inflammatory cytokines, TNFα, IL1-β, and IL-6, and immunomodulatory cytokines, IL22, IL23, and IL17." (PMID 37018237, 2023).
vitamin D deficiency (3 papers, 2019 to 2023). A nutritional condition produced by a deficiency of VITAMIN D in the diet, insufficient production of vitamin D in the skin, inadequate absorption of vitamin D from the diet, or abnormal conversion of vitamin D to its bioactive metabolites. "Statistically significantly higher levels of interleukin-22 were observed in the group of children with vitamin D deficiency compared to children with suboptimal and optimal vitamin D concentrations." (PMID 33435598, 2021). "The results of our study also showed a higher concentration of IL-22 in the group of patients with vitamin D deficiency compared to patients with the optimal concentration of vitamin D in blood." (PMID 33435598, 2021). "Therefore, it can be concluded that vitamin D deficiency adversely affects the development of an inflammatory infiltrate dependent on the production of IL-22." (PMID 33435598, 2021). "Furthermore, statistically higher levels of interleukin-22 were observed in the group of children with vitamin D deficiency (p = 0.01), suggesting a proinflammatory alert state." (PMID 33435598, 2021). "IL-22 treatment eliminated the effect of vitamin D deficiency on C. rodentium clearance." (PMID 30723466, 2019).
, and mouth disease (2 papers, 2017 to 2021). "IL-22 may have different pathological effects in hand, foot, and mouth disease that is caused by different pathogens." (PMID 34434945, 2021).
-dependent (2 papers, 2013 to 2019). "Therapeutic modulation of IL-22BPi2 and IL-22BPi3 production may be beneficial in IL-22-dependent disorders." (PMID 31108847, 2019).
acne inversa (2 papers, 2013 to 2014). "IL-22 deficiency may contribute to the pathogenesis of certain chronic disorders as postulated in this paper for acne inversa." (PMID 25297677, 2014). "IL‐22 deficiency in patients with acne inversa associated with defective AMP production and bacterial overgrowth is consistent with this interpretation and the importance of IL‐22 in microbial defence at mucosal sites." (PMID 24358364, 2013).
acute myeloid leukemia (2 papers, 2015 to 2018). Acute myeloid leukemia (AML) is a group of neoplasms arising from precursor cells committed to the myeloid cell-line differentiation. "In case that this association between ILC3 and susceptibility to GVHD is further confirmed in future independent cohorts, supplying acute myeloid leukemia patients with IL‐22 or IL‐22‐producing ILC3 might be a mean to prevent GVHD." (PMID 26228632, 2015). "Supporting this, appearance of IL-22-producing, gut-homing NKp44+ ILC3 in the blood of acute myeloid leukemia (AML) patients following conditioning treatment and hematopoetic stem cell transplantation (HSCT) is associated with protection against development of graft-versus-host disease (GVHD)." (PMID 29948108, 2018).
alcohol (2 papers, 2018 to 2022). "Since our previous results proved that LGG regulated IL-22 expression as well as ameliorated liver injury in the chronic plus binge ALD model, we wondered whether the amelioration of alcohol-induced liver injury by LGG was associated with IL-22 expression." (PMID 35603884, 2022).
alcohol abuse (2 papers, 2020 to 2023). The use of alcoholic beverages to excess, either on individual occasions ("binge drinking") or as a regular practice. "This study examined plasma levels of two key cytokines, Il-17 and Il-22, which construct the proinflammatory vs. anti-inflammatory axes across the spectrum of alcohol use disorder (AUD) and ALD including alcohol-associated hepatitis (AH) to determine the underlying status of the inflammation." (PMID 38162671, 2023). "Changes in IL-17 and IL-22 with alcohol abuse (pro-inflammatory), and thiamine as an anti-inflammatory therapy in our experiment provided potential proof of concept." (PMID 33737877, 2020).
alcoholic cirrhosis (2 papers, 2012 to 2013). "In this study, we report higher frequencies of circulating IL-22-producing CD4+CD45RO+ T cells in AH patients than in alcoholic cirrhosis patients and healthy controls." (PMID 23372820, 2013). "We measured the percentages of CD4+CD45RO+ T cells that produced IL-22 in the peripheral blood at baseline and detected a 1.7-fold increase in the frequency of these cells in AH patients compared with both alcoholic cirrhosis patients and healthy controls." (PMID 23372820, 2013). "Patients with chronic HBV, chronic HCV and alcoholic cirrhosis had significantly higher IL-22 serum levels than healthy controls (P = 0.009, P < 0.001 and P < 0.001, respectively)." (PMID 22967278, 2012).
alopecia areata (2 papers, 2021 to 2024). Loss of scalp and body hair involving microscopically inflammatory patchy areas. "Th17 cells secrete the pro-inflammatory cytokines such as IL-17, IL-22, and IL-23, which play important roles in the development of inflammatory and autoimmune diseases such as alopecia areata." (PMID 34943905, 2021). "A positive correlation was described between the serum level of IL-22 and the duration of alopecia areata as well as depression." (PMID 34943905, 2021). "In a majority of previously published studies the serum level of IL-22 in patients with alopecia areata was comparable with healthy controls." (PMID 34943905, 2021). "Further studies are needed to confirm the role of the serum IL-22 in alopecia areata." (PMID 34943905, 2021).
B-cell lymphoma (2 papers, 2020 to 2021). "IL-22 is involved in the pSS pathogenesis, wherein the IL-22/IL-22R pathway is implicated in the development of T and B-cell lymphoma." (PMID 34539411, 2021).
bladder tumor (2 papers, 2021 to 2023). "These intratumoral group 1 ILCs are associated with higher bladder tumor stage and exhibit a Th17‐like differentiation phenotype, marked by high expression of RORγt, IL‐17, and IL‐22 and low expression of Th1 and Th2 transcription factors and cytokines." (PMID 34496133, 2021). "In addition, IL-22 has been shown to promote PD-L1 expression through the activation of STAT3, and the anti-PD-L1 antibody nivolumab has been reported to be effective in bladder tumors with a high density of intratumoral IL22-producing cells." (PMID 38026978, 2023).
breast adenocarcinoma (2 papers, 2011 to 2012). "IL-22 could reduce the growth of mammary adenocarcinoma (EMT6) cells; this growth reduction was associated with the inhibition of ERK1/2 and Akt phosphorylation and the induction of G2/M phase cell cycle arrest." (PMID 21625390, 2011). "Conversely, IL-22 treatment induces the cell cycle arrest of murine breast adenocarcinoma EMT6 cells through the inhibition of ERK1/2 and AKT phosphorylation." (PMID 22922995, 2012). "A similar result was seen in the IL-22 treatment of murine breast adenocarcinoma EMT6, in which ERK1/2 phosphorylation was inhibited by IL-22, thus leading to cell cycle arrest." (PMID 22922995, 2012). "IL-22 inhibited the growth of human mammary adenocarcinoma EMT6 cells both in vivo and in vitro." (PMID 21625390, 2011).
bullous pemphigoid (2 papers, 2015 to 2025). Bullous pemphigoid (BP) is the most common form of autoimmune bullous dermatosis. "For example, high concentrations of IL-6, IL-22 and IL-23 were observed in IL-17+ neutrophils in bullous pemphigoid blister fluid." (PMID 26213975, 2015). "In this study, we aim to explore the relationship between serum levels of IL-17, IL-22, IL-25, EOS in peripheral blood, anti-BP180 antibodies, anti-BP230 antibodies, and IgE and disease activity and severity in patients with bullous pemphigoid." (PMID 40800128, 2025).
celiac disease (2 papers, 2018 to 2024). An autoimmune genetic disorder with an unknown pattern of inheritance that primarily affects the digestive tract. "We found, as in celiac disease, strong upregulation of IL-17 signaling and Th17 cell differentiation in EED including induction of IL21, IL6, IL17A IL17F, IL22, IFNG, IL21R, and IL2RA." (PMID 39300663, 2024). "Similarly, dysregulated ILC3 function and IL-22 secretion have been reported in celiac disease; however, further work is needed to determine whether disruption of ILC3 responses is a common pathway in sensitization and inflammation against a wide range of microbial, environment, and dietary factors." (PMID 29737384, 2018). "Inflammatory ILC producing IFN-γ and TNF-α have been described in biopsies taken from celiac disease patients; however, it is currently unclear whether ILC3-derived cytokines—particularly IL-22—maintain tolerance to dietary gluten under homeostatic conditions." (PMID 29737384, 2018).
Cerebral ischemia (2 papers, 2021 to 2023). Restriction of arterial blood supply to the brain associated with insufficient oxygenation to support the metabolic requirements of the tissue. "JAK2-STAT3 signaling pathway plays a protective role in improving inflammation, oxidative stress and neuronal apoptosis after cerebral ischemia-reperfusion injury mediated by interleukin-22." (PMID 38154101, 2023).
cervical cancer (2 papers, 2015 to 2020). A primary or metastatic malignant neoplasm involving the cervix. "Flow cytometry was used to determine the expression of interferon gamma (IFN-γ), Interleukin-22 (IL-22), IL-17 in the peripheral blood of healthy controls (HC), CIN and cervical cancer patients." (PMID 26474968, 2015). "It acts by secreting protease IV (PIV) and inactivating interleukin 22 (IL-22) in order to disrupt the mucosal defense against extracellular pathogens, providing opportunities for HPV infection, then promote the occurrence of cervical cancer." (PMID 33365275, 2020).
Chagas disease (2 papers, 2016). A parasitic infection caused by Trypanosoma cruzi. "Therefore, we examined the role of IL-22 in experimental Chagas disease using the reticulotropic Tulahuen strain of T. cruzi." (PMID 27650379, 2016).
cholangitis (2 papers, 2013 to 2024). An acute or chronic inflammatory process affecting the biliary tract. "In contrast, the cholangitis in IL-17A−/− and IL-22−/− mice was significantly attenuated as evaluated by portal inflammation and bile duct damage." (PMID 24040208, 2013). "Since the occurrence of cholangitis was completely abrogated only in p40−/− mice but not in Th17-deficient mice (p19−/−, IL-17A−/− and IL-22−/−) and Th1-deficient p35−/− mice, we next attempted to determine the role of IFN-γ in the induction of cholangitis." (PMID 24040208, 2013). "In the studies reported herein, we further demonstrate that IL-22−/− tends to decrease cholangitis." (PMID 24040208, 2013).
chronic pancreatitis (2 papers, 2018 to 2024). A chronic inflammatory process causing damage and fibrosis of the pancreatic parenchyma. "In a murine model of chronic pancreatitis, exposure to cigarette smoke resulted in increased IL22 production in T cells, promoting pancreatic fibrosis and contributing to the development of chronic pancreatitis." (PMID 38612627, 2024). "In cerulein‐induced chronic pancreatitis, IL‐22 administration with adenovirus ameliorated damage, and IL‐22 deficiency in IL‐22 KO mice or blocking endogenous IL‐22 with monoclonal anti‐IL‐22 was associated with worse acinar damage." (PMID 29713472, 2018).
chronic rhinosinusitis (2 papers, 2015 to 2021). Chronic form of sinusitis. "Previous genetic studies have shown that patients with chronic rhinosinusitis have reduced expression of the Interleukin-22 (IL-22) gene." (PMID 31879195, 2021).
colon adenocarcinoma (2 papers, 2020 to 2021). "LRG1 expression can be induced by TNF-α, IL-6, and IL-22 in human colon adenocarcinoma cell line." (PMID 32249825, 2020).
Constipation (2 papers, 2021 to 2022). Infrequent or difficult evacuation of feces. "It is worth noting that the tendency of IL-22 was diverted as it peaked in the rhubarb group and fell in the constipation group." (PMID 36545319, 2022). "We found the reduced levels of TGF-β, IL-10, and IL-21, and the increased levels of GM-CSF, IL-17A, IL-17F, IL-22, and IL-23 in the serum of constipation EAE mice." (PMID 34301274, 2021). "We found that the concentrations of TGF-β, IL-10, and IL-21 were decreased while the levels of GM-CSF, IL-17A, IL-17F, IL-22, and IL-23 were increased in constipation EAE mice and FMT EAE mice compared to EAE mice." (PMID 34301274, 2021). "And the results indicated that the IL-22 concentration in serum dropped in the constipation group and peaked in the rhubarb group, which implied that rhubarb might play a protective role through increasing IL-22 levels." (PMID 36545319, 2022). "Moreover, the serum levels of TGF-β, IL-10, and IL-21 were decreased while the GM-CSF, IL-17A, IL-17F, IL-22, and IL-23 were increased in the constipation EAE mice." (PMID 34301274, 2021).
cryptococcosis (2 papers, 2013 to 2024). An acute or chronic, localized or disseminated infection by Cryptococcus neoformans. "Interestingly, IL-22 deficient animals also show reduced IL-33 production in the lungs, which may lead to decreased Th2 axis activation during cryptococcosis and a lower presence of allergic-type responses." (PMID 39635124, 2024). "Therefore, we showcase a role of the IL-22 cytokine as a key factor for the retainment of R265 infection in the lungs and in limiting intensive lung inflammation during R265 cryptococcosis." (PMID 39635124, 2024). "Thus, the interplay between the immune lung microenvironment and the impact into the lung barriers during the cryptococcal infection emerges as a crucial point of convergence for the IL-22 role." (PMID 39635124, 2024). "Notably, unlike C. neoformans, R265 also induces a more pro-inflammatory cytokine profile and IL-22 production, thereby modulating the lung microenvironment differently than other cryptococcal infections." (PMID 39635124, 2024). "This argues against a Th17 response to cryptococcal infection as we hypothesized, but rather to an exclusively IL-22 producing subset of Th-cells." (PMID 23383232, 2013). "Accordingly, IL-22 functions, comprise not only for healing and tissue repair of epithelial barriers, but also for inducing β-defensin production in the alveoli spaces during cryptococcosis control, also improving tight junction formation and decreasing inflammatory responses." (PMID 39635124, 2024). "However, to confirm these speculations, further research should be attempted to identify the role of IL-22 and Th22 cells in clinical patients with cryptococcosis." (PMID 23383232, 2013).
cutaneous candidiasis (2 papers, 2017 to 2023). Candidiasis of the skin manifested as eczema-like lesions of the interdigital spaces, perleche, or chronic paronychia. "Not only IL-17-deficient but also IL-23-deficient mice exhibit a suppressed host defense against cutaneous candidiasis compared with IL-12- or IL-22-deficient mice." (PMID 38137722, 2023).
demyelination (2 papers, 2015 to 2024). "The involvement of IL-22 in the myelination process was assessed through in vivo experiments by using a murine demyelination model (Cuprizone mouse model)." (PMID 39040539, 2024). "To provide a more comprehensive understanding of the role of IL-22, we investigated its effect on remyelination in a mouse model of demyelination induced by Cuprizone." (PMID 39040539, 2024).
dry eye (2 papers, 2017 to 2022). "Increases of IFN-γ, IL-2, IL-4, IL-5, IL-13 or IL-β1 in SAC; TSLP in both PAC and SAC; and IL-17, IL-21 and IL-22 in dry eyes have been observed in different studies." (PMID 35935953, 2022). "We therefore investigated the effect of IL-22-secreting ILC3 cells on epithelial damage in the dry eye model." (PMID 28837629, 2017). "The increase in ILC3 cells in the draining lymph nodes and the increased IL-22 expression in the intraorbital glands after anti-HMGB1 treatment suggest a possible role for ILC3s in the improvement of dry eye in this model." (PMID 28837629, 2017). "Furthermore, the data also suggest that the improvement in dry eye in NOD.B10.H2b mice may involve an increase in IL-22-secreting ILC3s, rather than modulation of B or plasma cells." (PMID 28837629, 2017).
enterocolitis (2 papers, 2021 to 2023). An inflammatory process affecting the small intestine and colon. "It is also found that downregulation of CYP1A2 is observed during inflammation, whereas AhR activation protects intestinal epithelium from enterocolitis by promoting CYP1A2 expression, and that indole derivatives activate AhR to promote IL-22 secretion, which boosts intestinal mucosal defense." (PMID 37344888, 2023). "IL-22 knock out mice, although not developing enterocolitis spontaneously, also have an altered microbial composition and increase of epithelial-adherent bacteria, mainly caused by a decrease in mucin and anti-microbial peptide production." (PMID 34603258, 2021).
gastric diseases (2 papers, 2014 to 2025). "IL-22 has complex roles in gastric pathology, as it can promote epithelial regeneration and barrier function but also drive inflammation and hyperplasia; its dual effects in this model reflect the complexity of IL-22 signaling in human gastric diseases." (PMID 40673273, 2025). "Based on the in vitro data and the clinical observation in this study, IL-22 appears to play a beneficial and/or protective role in H. pylori-induced gastric diseases, preventing overproduction of inflammatory cytokines and maintaining the homeostasis of gastric immunity." (PMID 24824519, 2014). "Taken together, IL-22 likely plays a role in H. pylori-induced gastric diseases." (PMID 24824519, 2014).
gastric tumor (2 papers, 2020 to 2024). "Patients with gastric tumors have also been shown to have increased levels of circulating T cells secreting IL-22 as well as IL-17, thus showing a positive association with tumor progression." (PMID 33042126, 2020). "A SNP was found in the IL22 locus which was linked to an increase of about 2.5-folds in the risk of development of gastric tumors." (PMID 33042126, 2020). "Furthermore, IL-22 has also been described to aid metastasis of gastric tumor cells via increasing the expression of matrix metallopeptidases." (PMID 33042126, 2020).
glioma (2 papers, 2020 to 2021). A benign or malignant brain and spinal cord tumor that arises from glial cells (astrocytes, oligodendrocytes, ependymal cells). "Interleukin (IL)-22, a member of pro-inflammatory cytokines, was involved in glioma genesis via JAK/STAT signaling." (PMID 34439380, 2021). "Correspondingly, by using anti-IL-22 antibody or in IL-22 knock-out mice, the decreased IL-22 expression exhibited protective roles in the development of glioma." (PMID 33042126, 2020). "In addition, IL-22 treated glioma cells triggered activation of STAT3 and PI3K-Akt phosphorylation and increased anti-apoptotic protein Bcl-xL level." (PMID 34439380, 2021). "Murine model of glioma illustrates that increased IL-22 levels in brain can worsen the symptoms." (PMID 33042126, 2020).